IL6 (interleukin 6)
Diseases named in the same sentence as IL6 in open-access papers (continued):
Sharing a sentence is not in itself a finding about the gene and the disease.
lung disease (continued). "The ROC analysis revealed a good area under the curve for circulatory C1INH to discriminate neonatal lung disease group from healthy neonates, and this discriminative ability was enhanced when combined with the traditional circulatory marker levels of IL-6 and CRP." (PMID 35669402, 2022). "Moreover, NLRP3-derived cytokines (e.g., IL-1β, IL-18) appear to be the main inducers of a cytokine cascade (involving IL-23, IL-17, IL-26, IL-6, IL-13, and IL-5) that is responsible for the development of pulmonary diseases in morbidly obese subjects." (PMID 35806353, 2022). "An increased pro-inflammatory, IL-6 driven response after treatment with antibiotics could thus contribute to development or severity of pulmonary diseases." (PMID 33147273, 2020). "In particular, salivary IL-6 and IL-8 could represent useful biomarkers for monitoring lung disease in CF children." (PMID 32234058, 2020). "Plasma and/or bronchoalveolar levels of IL-6 have been identified as early biomarkers of lung injury and predictive factors of prolonged mechanical ventilation, organ dysfunctions, morbidity and mortality in lung diseases." (PMID 32475230, 2020). "IL-6 can play a positive role in some specific aspects of lung disease." (PMID 29674943, 2018). "Characterizing the mechanism of IL-6 in affecting frailty, lung disease (specifically COPD), and adverse outcomes may prove to be an important field of future research." (PMID 30380761, 2018). "IL-6, a proinflammatory cytokine, has been shown to be elevated in different lung diseases." (PMID 29941022, 2018). "When assessing smoking related pulmonary disease, biomarkers of inflammation such as IL-2, IL-6, IL-8, and eotaxin may add additional modest predictive value on top of clinical variables alone." (PMID 29065892, 2017). "IL-6 is regarded as an active factor and an ongoing inflammatory marker of many lung diseases." (PMID 26161235, 2015). "We selected H2O2 and IL-6 as biological markers due to the fact that these have been widely used in many studies to evaluate the oxidative and immune changes occurring in smoker subjects and patient with lung diseases." (PMID 25889552, 2015). "Furthermore, we demonstrate that pharmacologic inhibition or genetic removal of IL-6 attenuates pulmonary inflammation, fibrosis and air-space destruction in this model of adenosine driven lung disease." (PMID 21799929, 2011). "In addition, T-helper (Th)-17 cells induced the production of pro-inflammatory IL-17, and are implicated in the pathogenesis of lung disease, and their activation in the presence of a combination of TGF-β, IL-6, and IL-1β mediated these pro-inflammatory differentiation." (PMID 36877411, 2023). "In addition, pro-inflammatory pathways as that involving interleukin 6 (IL-6), could be a severity predictor of lung diseases." (PMID 32527257, 2020). "Indeed, the concept that the role of IL-6 signaling may differ between acute and chronic stages of lung disease is suggested." (PMID 26289430, 2015). "Thus, although cause and effect cannot be established, our results suggest that blocking IL-6 signaling during chronic stages of lung disease can attenuate the production of key effector molecules and the loss of barrier function, both of which likely impact the remodeling processes seen." (PMID 21799929, 2011). "In addition, higher IL-6 plasma levels suggest that inflammation could explain the more aggressive pulmonary disease in patients with alveolitis." (PMID 16107215, 2005). "TNFα is a potent pro-inflammatory cytokine involved in several pulmonary disorders such as IPF; it led to an increase in IL-6 expression in both cell types." (PMID 41155824, 2025). "IL-6, IL-1β, MIP-2, and iNOS are well known to be important for the development and worsening of lung disease." (PMID 39052574, 2024). "IL-6 and TNF-α were investigated due to being prevalent in pulmonary diseases and as a result of long-term vaping." (PMID 38339063, 2024).
lung disease (continued). "Previously, we described elevated levels of cytokines/chemokines such as IL-18, IFN-γ, CXCL-10, CXCL-9, G-CSF, IL-6, CXCL-1, VEGF, and PDGF-BB in plasma samples of tuberculosis (TB) patients with active pulmonary disease." (PMID 37685858, 2023). "Lung diseases can be further aggravated by inflammatory cytokines such as CCL2 and interleukin (IL)-6." (PMID 38004123, 2023). "Tests for pulmonary disease include a non-invasive induced sputum analysis, in particular for B-cell activating factor (BAFF), interleukin-6 (IL-6), and interleukin-8 (IL-8)." (PMID 36675090, 2023). "IL-6, TNF-α, IL-1β, and MIP-2 are representative pro-inflammatory cytokines and chemokines that are related to the pathogenesis of various lung diseases." (PMID 35326218, 2022). "Up to date, it has been shown that in pulmonary diseases marked by inflammatory features, a typical raise in serum CRP level takes place in response to inflammatory cytokines such as interleukin (IL)-6, IL-1 or tumoral necrosis factor (TNF)-α." (PMID 35809152, 2022). "MIF controlled the production of other cytokines such as IL-1β, IL-6, IL-8 and TNF-α in neonatal lung diseases." (PMID 33356032, 2021). "These preliminary results suggest that salivary IL-6 and IL-8 levels increase during the acute phase of sinonasal disease (i.e., NTH), while the end stages of pulmonary disease and sinonasal disease (i.e., NP) show decreased TNF-α levels." (PMID 32326546, 2020). "These include CD14, CD40, and CD80, which are surface receptors that trigger NF-κB activation, and IL-8, IL-6, and RANTES that are NF-κB-responsive cytokines with major roles in the pathogenesis of CF lung disease." (PMID 32528461, 2020). "Specifically, our results suggest that salivary IL-6 and IL-8 levels increase during the acute phase of sinonasal disease (i.e., NTH), while the end stages of pulmonary disease and sinonasal disease (i.e., NP) show decreased TNF-α levels." (PMID 32326546, 2020). "Genes showing altered expression include a number of genes known to play important roles in lung disease such as α1-antitrypsin (SERPINA1), transforming growth factor β 1 (TGFβI), interleukin 1 receptor 1 (IL1R1) and IL6, IL8, IL1B, IL1A." (PMID 28335732, 2017). "Nevertheless, other studies have reported associations between a number of cytokines, such as TNF-α, IL-1β, IL-6, IL17 and TGF-β1, and radiographic TB lung disease presentation." (PMID 27494953, 2016). "Indeed, systemic inflammation might be the link between HDL-cholesterol, LDL-cholesterol and lung function, since the levels of the general inflammation markers C-reactive protein (CRP), interleukin-6 (IL-6) and other markers of inflammation were shown to be increased in lung disease." (PMID 26421427, 2015). "In the pathogenesis of bleomycin-induced lung disease, transforming growth factor-β (TGF-β), tumor necrosis factor-α (TNF-α), IL-1, IL-5, IL-6, platelet-derived growth factor (PDGF) and a variety of cytokines such as chemokines play important roles." (PMID 23558450, 2013). "Thus, the role of IL-6 signaling may differ between acute and chronic stages of lung disease." (PMID 21799929, 2011). "IL-6 has been regarded as a biomarker for discriminating NTM and other lung disease." (PMID 40034169, 2025). "In addition, our study contributes to a more accurate understanding of the role of IL-6 in ASS and DM-related lung diseases." (PMID 36199667, 2022). "It should be stressed that IL-6, as an activator of the JAK-STAT signaling pathway, can act as either pro-inflammatory as well as an anti-inflammatory factors in autoimmune and/or inflammatory diseases, including lung diseases." (PMID 34815425, 2021). "A large number of biomarkers with the potential to detect lung disease were investigated in the literature summarised in this review, including (but not limited to): Club/Clara cell protein 16 (CC16); serum HO-1; IL6; TNFα, IL6, and IL8; and Npnt." (PMID 34360414, 2021).
lung disease (continued). "We found that SAHA significantly (p < 0.05) diminishes Pa-LPS induced systemic IL-6 and MPO levels, suggesting its potential as a therapeutic for controlling chronic inflammation and neutrophil-activation mediated obstructive CF-lung disease." (PMID 29301535, 2018). "Neutralization of pro-inflammatory cytokines such as IL-6, TNF-α, VEGF, and IFN-α/β, as well as anti-inflammatory IL-4, during severe pulmonary disease may help reduce ongoing parenchymal damage in the MTB-infected lung." (PMID 28125719, 2017). "The reduction of IL-6 and MIP-1α observed in BALF are of specific interest, due to the reported direct correlation of IL-6 and MIP-1α with clinical symptoms in animal and human RSV lung disease." (PMID 26010881, 2015). "The associations between both EEV and MEV and disease severity, and between EEV and IL-6, suggest a significant interplay between pulmonary disease and inflammation, with non-respiratory cells (endothelial cells and monocytes) involvement, along with the progression of the disease." (PMID 34768536, 2021). "Specifically, the identical behavior of both EV and IL-6 levels from group A to D suggests the presence of a significant interplay between pulmonary disease and inflammation, with non-respiratory cells (in particular, endothelial cells and monocytes) involvement." (PMID 34768536, 2021). "Collectively, the use of plasma markers of systemic inflammation, especially IL-6 and CRP, provides additional indicators of clinical status and may add to our understanding of the relationship between inflammation and the severity of lung disease in CF patients." (PMID 22333132, 2012). "Plasma levels of IL-6, tumor necrosis factor, IL-10, and IL-1 receptor antagonist remained low after 1 h of IMV in 39 adults with no previous lung disease." (PMID 35844745, 2022).
malnutrition (153 papers, 2009 to 2026). Inadequate nutrition resulting from poor diet, malabsorption, or abnormal nutrient distribution. "IL-6 can also cause malnutrition by increasing protein catabolism and eating behavior, and indeed, anorexia in patients on hemodialysis or with kidney disease is associated with higher levels of IL-6." (PMID 40243751, 2025). "Low albumin levels are linked to an increased risk of malnutrition, reduced OS, and elevated inflammatory markers such as interleukin-6 and C-reactive protein." (PMID 40678069, 2025). "This dual nature underscores the importance of contextual clinical correlation when utilizing IL-6 in malnutrition risk algorithms." (PMID 40611154, 2025). "In the group of subjects at risk of malnutrition, the sample median is shifted toward lower Il-6 concentrations, associated with the subjects’ normal nutritional status." (PMID 40094974, 2025). "IL-6 appears to be associated with well-known prognostic variables such as malnutrition, performance status, and severe illness." (PMID 41179937, 2025). "In contrast to the Karnofsky index and malnutrition—which were likely excluded due to their strong association with elevated IL-6 and reduced IFN-γ—age and severe diseases such as lung cancer (LC) retained their prognostic significance." (PMID 41179937, 2025). "GNRI-defined malnutrition associated with higher mortality, likely reflecting impaired immunity from hypoalbuminemia and inflammation from cytokines like IL-1, IL-6, and TNF-α24,25." (PMID 37845294, 2023). "In the current study, significant associations of IL-6 to malnutrition were only found using ROC curve cut-offs for the biomarker and categories for the malnutrition assessment." (PMID 37906352, 2023). "High IL-6 levels contribute to dialysis-associated malnutrition and are prognostic of cardiovascular risk, which is an adverse outcome of hemodialysis." (PMID 35456352, 2022). "On the one hand, low body weight and the associated malnutrition can exacerbate inflammation, expressed by elevated IL-6 levels." (PMID 36235613, 2022). "Combining prealbumin with inflammatory markers such as CRP or interleukin-6 (IL-6) could improve its diagnostic accuracy by helping to differentiate malnutrition from inflammation-induced hypo-prealbuminemia." (PMID 41036189, 2025). "Apparently, the CONUT score could be helpful for identifying CD patients with moderate/severe malnutrition risk (CONUT ≥ 5), showing that reduced PhA values and increased IL-6 levels emerged as independent predictors of malnutrition risk." (PMID 37111172, 2023). "Finally, increased IL-6 levels and reduced PhA values were identified as independent predictors of moderate/severe malnutrition risk (p < 0.05)." (PMID 37111172, 2023). "Moreover, we identified IL-10 as an inflammatory determinant for associated morbidity and that IL-6-572 G/C and IL-10-1082 A/G SNPs contribute to the severity of malnutrition–inflammation and depressive symptoms." (PMID 37763079, 2023). "Finally, in this sample, IL-6 levels increased with decreasing PhA values, and both parameters were meaningful predictors of moderate/severe malnutrition risk." (PMID 37111172, 2023). "Third, while the use of IL-6 as a predictive factor contributes to the model’s predictive value, its specificity to malnutrition versus systemic inflammation requires careful interpretation in clinical contexts." (PMID 40611154, 2025). "While IL-6 demonstrated predictive value in our model, its specificity to malnutrition versus systemic inflammation requires clarification." (PMID 40611154, 2025). "IL-6 alone, or with hs-CRP, has also been associated with all-cause and cardiovascular mortality in other studies, and it was a superior predictor of malnutrition compared with other cytokines in ESRD." (PMID 40004669, 2025).
malnutrition (continued). "The results indicate that decreased levels of albumin (<3 g/dL) and hemoglobin (<11 g/dL), along with elevated homocysteine, CRP, IL-6 (>7.5 pg/mL), and IP-10 (>250 pg/mL), should alert medical professionals to potential malnutrition in hospitalized patients." (PMID 40094974, 2025). "HF patients often experience malnutrition and inflammatory complications, which lead to increased release of interleukin-2 and interleukin-6." (PMID 39659906, 2024). "In both groups, malnutrition and being overweight were significantly associated with higher CRP and IL-6 values (Student’s t-test, both p < 0.05)." (PMID 37887395, 2023). "It has been shown that inflammatory factor expression is significantly upregulated in hypertensive patients, such as IL-6 and TNF-α, and malnutrition is associated with the activation of inflammatory factors." (PMID 37465450, 2023). "In both groups, malnutrition and overweight were significantly associated with higher CRP and IL-6 values (both, p < 0.05)." (PMID 36904249, 2023). "The C allele of IL-6-572 G/C presented a small effect (GC–GG, δ = 0.27) on the MIS score; in contrast, the GG genotype of IL-10-1082 A/G showed a small effect on malnutrition–inflammation severity (GG–AA, δ =0.37)." (PMID 37763079, 2023). "In cancer and cancer-related malnutrition, high production of cytokines such as TNF-α, IL (interleukin) -2, and IL-6 cause metabolic disruption which inhibits albumin gene expression and causes vascular permeability." (PMID 36869395, 2023). "In patients with ESKD, highly-sensitive CRP and interleukin-6 (IL-6) levels best predict malnutrition, while serum albumin, IL-6, and fetuin A levels best predict mortality." (PMID 37784041, 2023). "Conversely, increased levels of CRP and its end products, tumor necrosis factor-alpha (TNF-α) and interleukin-6 (IL-6), lead to decreased levels of the malnutrition marker albumin." (PMID 37760482, 2023). "Our review also found that SPA is negatively related to levels of CRP and IL-6, two positive indicators of malnutrition." (PMID 36615707, 2022). "Individuals with comorbidities, combination of medicine, eczema history, malnutrition, elevated blood IL-6 and hs-CRP, older age, lower education level, longer medication and lower medication literacy were more likely to suffer severe rash." (PMID 35505288, 2022). "Individuals with comorbidities, combined drug application, eczema history, malnutrition, elevated blood IL-6 and hs-CRP levels, older age, lower education level, worse medication literacy were more likely to have severe skin ADRs." (PMID 35505288, 2022). "Individuals with comorbidities, a combination of medicine, malnutrition, elevated blood IL-6, lower education level, and lower medication literacy were more likely to have severe HFS." (PMID 35505288, 2022). "Studies report that malnutrition can lead to fluid overload and accumulation of inflammatory markers such as Interleukin 6 and tumor necrosis factor-alfa, thus aggravating postoperative infections." (PMID 35108317, 2022). "The expression of Il1b and Tnf following LPS challenge was amplified in malnourished mice, whereas malnutrition blunted LPS-induced Il6 expression." (PMID 35983045, 2022). "Malnutrition has been shown to interact with many important wound healing pathways, including upregulation of IL-6 and TNF-a, as well as inhibiting collagen synthesis." (PMID 33850181, 2021). "In the present study, we showed that malnutrition was related to the increased IL-6 and NLR levels and was a strong prognostic indicator for esophageal-SCC patients." (PMID 34578883, 2021). "WAT contains large lipid droplets and releases adipokines (FFAs, TNF-α, IL-6, IL-10, resistin, leptin, and adiponectin) to maintain metabolic homeostasis and stores TG for future energy production during periods of malnutrition." (PMID 33947969, 2021). "Previous studies have demonstrated a relationship between malnutrition and elevated levels of IL-6 and TNFα." (PMID 32297262, 2020).